NFIB (nuclear factor I B)
Diseases named in the same sentence as NFIB in open-access papers (continued):
Sharing a sentence is not in itself a finding about the gene and the disease.
lymph node metastasis (2 papers, 2018 to 2023). "The Chi-square test revealed that high NFIB expression was significantly correlated with higher T-stage (P = 0.012) and lymph node metastasis (P = 0.028) in CRC." (PMID 37491379, 2023). "Chi‐square test revealed that high NFIB expression significantly correlated with lymph node metastasis (P = 0.014) and advanced TNM stage (P = 0.036) in EJA." (PMID 29577671, 2018). "On the other hand, high NFIB expression correlated with lymph node metastasis, advanced TNM stage, and short OS and DFS in patients with EJA." (PMID 29577671, 2018). "Additionally, NFIB was highly expressed in cancer tissues with lymph node metastasis in comparison with those without lymph node metastasis." (PMID 29577671, 2018). "High NFIB but not NFIA expression correlated with poor differentiation, lymph node metastasis, and short OS and DFS time in patients with EJA." (PMID 29577671, 2018).
Macrocephaly (2 papers, 2021 to 2022). Occipitofrontal (head) circumference greater than 97th centile compared to appropriate, age matched, sex-matched normal standards. "Mutations in NFIB are known to cause disability and macrocephaly." (PMID 35433561, 2022).
oral cancer (2 papers, 2023 to 2025). "Exosomal miR-626 enhances the proliferation and migration of oral cancer cells by targeting nuclear factor I/B (NFIB)." (PMID 36612314, 2023).
ovarian carcinoma (2 papers, 2023). A malignant neoplasm originating from the surface ovarian epithelium. "Because miRNA3652 is downregulated in ovarian cancer cells, NFIB and SIK2 are increased, which causes ovary cells to produce reactive metabolites, mutagenic DNA adducts, and free radicals." (PMID 37845675, 2023). "Silencing of circ_PIP5K1A overcame cisplatin resistance via sponging miR-942-5p and targeting NFIB expression in ovarian cancer." (PMID 38152652, 2023). "Downregulation of circ_0007841 led to promotion of cisplatin sensitivity via inhibition of NFIB expression by sponging miR-532-5p in ovarian cancer." (PMID 38152652, 2023). "In addition, upregulation of miR-506-3p reduced cell resistance to PTX in ovarian cancer cells, which can be reversed by elevation of NFIB." (PMID 38152652, 2023).
psoriasis (2 papers, 2024 to 2025). An autoimmune condition characterized by red, well-delineated plaques with silvery scales that are usually on the extensor surfaces and scalp. "A significant finding supporting the hair follicle-immune cell axis in psoriasis is the involvement of the transcription factor NFIB in the maintenance and regeneration of hair follicles." (PMID 38289616, 2024). "Although NFIB has not been linked to psoriasis or other autoimmune diseases, a recent study in chicken cells showed that its overexpression increased inflammatory cytokine levels via activation of the NF-κB pathway, mediated by upregulation of RIP2." (PMID 41153410, 2025).
salivary gland adenoid cystic carcinoma (2 papers, 2020 to 2023). An adenoid cystic carcinoma arising from the salivary gland. "Nevertheless, the NFIB mRNA expression level was significantly elevated in salivary gland adenoid cystic carcinoma in FriersonHF’s dataset." (PMID 32219034, 2020).
acute liver failure (1 paper, 2018). Rapid deterioration of liver function causing encephalopathy and coagulopathy. "miR-1224 inhibited hepatocyte proliferation and survival in acute liver failure by targeting the antiapoptotic gene nuclear factor I/B (NFIB)." (PMID 29701719, 2018).
aniridia (1 paper, 2025). Aniridia is a congenital ocular malformation characterized by the complete or partial absence of the iris. "PAX6 is a master regulator of eye development and retinal patterning; a mutation to this gene can cause aniridia and other ocular or systemic issues, whilst NFIB is a downstream target of PAX6 that plays a key role in retinal development and photoreceptor differentiation." (PMID 40817596, 2025).
autism (1 paper, 2026). Persistent deficits in social interaction and communication and interaction as well as a markedly restricted repertoire of activity and interest as well as repetitive patterns of behavior. "Remarkably, de novo regulatory genes (POGZ, NFIB) are previously identified autism risk genes in large scale sequencing studies, providing validation of dosage sensitivity mechanisms." (PMID 42281968, 2026).
autism spectrum disorder (1 paper, 2021). A spectrum of developmental disorders that includes autism, and Asperger syndrome. "A previous study reported that individuals haploinsufficient for NFIB showed muscle tone regression, motor and language deficits, attention deficit disorder, autism spectrum disorder, and behavioral abnormalities." (PMID 34783303, 2021).
Barrett esophagus (1 paper, 2020). Esophageal lesion lined with columnar metaplastic epithelium which is flat or villiform. "In Kim’s study, the NFIB mRNA expression level was also downregulated in esophageal adenocarcinoma and Barrett’s esophagus." (PMID 32219034, 2020).
bladder cancer (1 paper, 2020). "Reduced mRNA expression of NFIA, NFIB and NFIX predicted better OS in bladder cancer." (PMID 32219034, 2020).
Bladder urothelial carcinoma (1 paper, 2020). "Bladder urothelial carcinoma patients with NFIB gene alteration showed significantly better OS compared with bladder urothelial patients without NFIB gene alteration." (PMID 32219034, 2020).
Brain Malformation (1 paper, 2022). "We used WES to explore genetic lesions in a fetus with unexplained brain malformation and lung lobulation defects and identified a novel non-sense mutation of NFIB (NM_001190737:c.870C > A;p.Tyr290*)." (PMID 35433561, 2022).
callosal agenesis (1 paper, 2023). "Interestingly, haploinsufficiency of the NFIB and NFIX genes also causes callosal agenesis, and missense mutations in the NFIX gene have been associated with Sotos-like features." (PMID 37915986, 2023).
cervical squamous cell carcinoma (1 paper, 2020). A squamous cell carcinoma arising from the cervical epithelium. "NFIB expression was downregulated in high grade cervical squamous and cervical squamous cell carcinoma analyzed according to Zhai and Scotto’s datasets, respectively." (PMID 32219034, 2020). "The results showed lower mRNA expression of NFIB, NFIC and NFIX predicted worse OS in cervical squamous cell carcinoma." (PMID 32219034, 2020).
clear cell sarcoma of the kidney (1 paper, 2020). "NFIB was overexpressed in clear cell sarcoma of the kidney and papillary renal cell carcinoma according to Cutcliffe and Jones’s datasets." (PMID 32219034, 2020).
colon adenoma (1 paper, 2020). An adenoma that arises from the colon. "NFIB mRNA level was upregulated in colon adenoma according to Skrzypczak’s dataset." (PMID 32219034, 2020).
diabetic nephropathy (1 paper, 2025). "The downregulation of CDC25A, E2F3, and NFIB increases the risk of developing diabetic nephropathy." (PMID 40041782, 2025).
dilated cardiomyopathy (1 paper, 2024). Cardiomyopathy which is characterized by dilation and contractile dysfunction of the left and right ventricles. "Endothelial cell analysis further revealed COL25A1, NFIB, and KLF7 as significant genes for dilated cardiomyopathy, hypertrophic cardiomyopathy, and Tetralogy of Fallot." (PMID 39202774, 2024).
Ewing sarcoma (1 paper, 2024). A small round cell tumor that lacks morphologic, immunohistochemical, and electron microscopic evidence of neuroectodermal differentiation. "Taken together, our results in SKNMC and NCI-H446 cells show that DisP-seq can effectively detect TFs with prominent IDRs in various cellular contexts and that NFIB can be a major determinant of the DisP-seq landscape outside of Ewing sarcoma." (PMID 37037903, 2024). "In contrast, NFIB peak locations in DisP islands associated with EWS-FLI1 in SKNMC cells show low signals in all ENCODE cell types, suggesting that they are associated primarily with the Ewing sarcoma pathologic state." (PMID 37037903, 2024). "In wild-type SKNMC cells, NFIB is partially sequestered by EWS-FLI1 in pathologic DisP islands, which are exclusively observed in the context of Ewing sarcoma." (PMID 37037903, 2024).
fibrosis (1 paper, 2025). the formation of excess fibrous connective tissue in an organ or tissue in a reparative or reactive process. "Clinical examination of liver tissues from MASH fibrosis patients corroborated diminished NFIB expression in HSCs across varying fibrosis stages." (PMID 41436407, 2025).
head and neck cancer (1 paper, 2020). A primary or metastatic malignant neoplasm affecting the head and neck. "Decreased expression levels of NFIA, NFIB and NFIC were associated with poor overall survival (OS) in head and neck cancer." (PMID 32219034, 2020).
head and neck squamous cell carcinoma (1 paper, 2020). A squamous cell carcinoma that arises from any of the following anatomic sites: lip and oral cavity, nasal cavity, paranasal sinuses, pharynx, larynx, and salivary glands. "In Cromer’s dataset, NFIB mRNA was significantly decreased in head and neck squamous cell carcinoma." (PMID 32219034, 2020).
Hodgkins lymphoma (1 paper, 2022). A heterogeneous group of malignant lymphoid neoplasms of B-cell origin characterized histologically by the presence of Hodgkin and Reed-Sternberg (HRS) cells in the vast majority of cases. "PBX1 was upregulated in Hodgkin lymphoma and affected the differentiation of Hodgkin lymphoma cells by activating NFIB and TLX2." (PMID 35068042, 2022).
infiltrating bladder urothelial carcinoma (1 paper, 2020). An invasive transitional cell carcinoma that arises from the urinary bladder urothelium. "NFIA, NFIB and NFIC expressions were decreased in both superficial bladder cancer and infiltrating bladder urothelial carcinoma compared with normal tissues in Lee, Sanchez-Carbayo2 and Blaveri2’s studies." (PMID 32219034, 2020).
invasive breast carcinoma (1 paper, 2020). A carcinoma that infiltrates the breast parenchyma. "The gene expressions of ACOT7, STAT1, TYMP, and VOPP1 were significantly increased in invasive breast carcinoma, while the gene expressions of ACTG2, CNN1, CDC14B, NFIB, RCN1, and TRIM2 were dramatically downregulated in BRCA." (PMID 31986487, 2020).
kidney chromophobe cell carcinoma (1 paper, 2020). "In addition, two analyses with Yusenko’s dataset showed lower NFIB mRNA levels in chromophobe renal cell carcinoma and renal oncocytoma." (PMID 32219034, 2020). "In addition, expression of NFIA and NFIB was downregulated in kidney chromophobe cell carcinoma, whereas expression of NFIC and NFIX was upregulated." (PMID 32219034, 2020). "Contrary to kidney chromophobe cell carcinoma, expression of NFIA and NFIB was upregulated in kidney papillary cell carcinoma and expression of NFIC and NFIX was reduced." (PMID 32219034, 2020).
kidney clear cell carcinoma (1 paper, 2020). "Consistent with the trend observed in the Oncomine database, NFIA, NFIB and NFIX were significantly overexpressed in kidney clear cell carcinoma compared with normal kidney tissue." (PMID 32219034, 2020).
Liver Fibrosis (1 paper, 2025). "Our study reveals NFIB as the most markedly down-regulated transcription factor during HSCs activation, as evidenced by single-cell sequencing analysis of liver fibrosis." (PMID 41436407, 2025). "Subsequent RNA sequencing elucidated the mechanism by which NFIB operates in liver fibrosis." (PMID 41436407, 2025). "Using a murine model of liver fibrosis induced by a choline-deficient, amino acid-restricted high-fat diet (CDAHFD) and carbon tetrachloride (CCl4) exposure, we observed reduced fibrosis levels following NFIB overexpression." (PMID 41436407, 2025). "Specifically, NFIB is found to directly interact with the promoter region of the chemokine C─C motif ligand 5 (CCL5), suppressing its expression and thereby mitigating liver fibrosis by inhibiting oxidative stress." (PMID 41436407, 2025).
neural tumour (1 paper, 2016). "This analysis revealed that astrocytic markers displayed a significant positive correlation with NFIB mRNA expression in the mesenchymal and classical tumours but not the proneural and neural tumour subtypes." (PMID 27083054, 2016).
OFCD syndrome (1 paper, 2022). "A total RNA microarray revealed alterations in the expression of numerous genes in BCOR Mut PDL cells, several of which are implicated in transcriptional upregulation; NFIB, DLX5, and ZFPM2 were the most significantly upregulated genes in OFCD syndrome." (PMID 35957990, 2022).
preeclampsia (1 paper, 2015). Preeclampsia is a hypertensive disorder of pregnancy that is characterized by new-onset hypertension with proteinuria presenting after 20 weeks of gestation, and depending on mild or severe forms may initially present with severe headache, visual disturbances, and hyperreflexia. "Finally, two genes differentially expressed in PTB clinical subtypes and classified as fast evolving in each of the three categories, NFIB (preeclampsia and LED) and CXCR4 (sPTB)." (PMID 26641094, 2015).
promyelocytic leukemia (1 paper, 2014). "In human promyelocytic leukemia cell line HL-60, highly up-regulated expression of miR-21 can target NFIB and also NFIB negatively regulated miR-21 expression." (PMID 24949940, 2014).
prostate adenocarcinoma (1 paper, 2020). "The results showed NFIB expression was upregulated in prostate adenocarcinoma according to Wallace’s dataset, however, the opposite results were found in Tomlins’s study." (PMID 32219034, 2020).
prostatic hyperplasia (1 paper, 2024). "Additionally, NFIB has been found to interact with FOXA1 as a cofactor in regulating AR target gene expression, and loss of NFIB induces prostatic hyperplasia in a mouse model." (PMID 38778357, 2024).
rectal cancer (1 paper, 2021). A primary or metastatic malignant neoplasm that affects the rectum. "Studies reported that LINC00461 played an oncogenic role in CRC cells through the NFIB signaling pathway, and mediated cisplatin resistance of rectal cancer by targeting the miR-593-5p/CCND1 axis, showing that LINC00461 may be a prognostic biomarker for CRC." (PMID 33959151, 2021).
salivary gland cancer (1 paper, 2024). A primary or metastatic malignant neoplasm that affects the major or minor salivary glands. "Salivary gland cancer organoids recapitulated the parental tissue genotypic characterization, with >97.6% of all COSMIC annotated variants and all MYB, MYBL1, and NFIB gene rearrangements retained." (PMID 39309690, 2024).
serous ovarian cancer (1 paper, 2022). "Accordingly, overexpression of some acting on genes like FOSL2, NFIB, NFIC, and PROCR, which are associated with proliferation and metastasis, predicts poor prognosis in high-grade serous ovarian cancer." (PMID 35935940, 2022).
skin carcinoma (1 paper, 2023). "Among its tumor suppressor activities, NFIB acts as a barrier to skin carcinoma progression, and its down-regulation is associated with dedifferentiation and aggressiveness in LUAD." (PMID 37738673, 2023).
Tetralogy of Fallot (1 paper, 2024). A congenital cardiac malformation comprising pulmonary stenosis, overriding aorta, ventricular septum defect, and right ventricular hypertrophy. "As for Tetralogy of Fallot, NFIB (nuclear factor I B, 600728) was shown to be associated with such CHD subtype in infants through microRNA regulation, validating the efficacy and accuracy of our prediction." (PMID 39202774, 2024).
tongue squamous cell carcinoma (1 paper, 2020). A squamous cell carcinoma that arises from the tongue. "Ye’s dataset showed significantly decreased NFIA and NFIB mRNA expression level in tongue squamous cell carcinoma." (PMID 32219034, 2020). "In addition, expression of NFIB and NFIX was downregulated in tongue squamous cell carcinoma according to Estilo’s study." (PMID 32219034, 2020).
Wilms tumor (1 paper, 2020). An embryonal neoplasm characterized by the presence of epithelial, mesenchymal, and blastema components. "However, in Cutcliffe’s dataset, NFIB expression was reduced in Wilms tumor." (PMID 32219034, 2020).
tumor (100 papers, 2011 to 2026). "Lack of novel therapeutics is in part due to the unique biology of SCLC, which is driven by mutations in tumor suppressors and amplifications of transcription factors like NFIB and MYC." (PMID 36690626, 2023). "NFIB is a protein-coding gene associated with embryonic development, tumor growth, and brain development." (PMID 35393395, 2022). "High NFIB expression is associated with poor tumor grade, metastasis, and worse patient prognosis." (PMID 40943553, 2025). "PBX1 stimulates NFIB, an oncogene linked to several neoplasms, in HL cell lines, as demonstrated by elevated NFIB expression levels in the presence of PBX1 and diminished expression following PBX1 knockdown, thereby demonstrating PBX1’s direct regulatory effect on NFIB transcription." (PMID 41226583, 2025). "To determine the molecular mechanism underlying increased metastatic colonization driven by NFIB, we sequenced total mRNA of tumourspheres and primary tumours derived from Nfib high‐expression models (LM1 and LM9) and Nfib low‐expression models (HR1, LM1 Nfib KO and LM9 Nfib KO)." (PMID 33751828, 2021). "In vivo, combined NFIB suppression and ferroptosis induction significantly inhibit tumor growth and increase lipid peroxidation in CRPC xenografts." (PMID 41801221, 2026). "NFIB expression positively correlated with neuroendocrine (NE) markers and contributed to tumor heterogeneity, a process modulated by Notch1." (PMID 42001853, 2026). "The transcription factors TBX2 and NFIB were highly activated in the relapsed tumor subgroups (Subgroups 4 and 5), potentially playing profound roles in transcriptional regulation in the recurrence of HCC tumors." (PMID 40018995, 2025). "The contradictory effect of NFIB on tumor development and progression depends on the cellular and tissue molecular context." (PMID 38987822, 2024). "LINC00461′s expression in CRC is inconsistent; some studies show that its upregulation promotes tumor growth and proliferation via the miR-323b-3p/NFIB axis, while others suggest that it downregulates tumor progression via miR-141/PHLPP2." (PMID 37760852, 2023). "Together, these data argue that CARM1 regulates SCLC tumor growth via methylation of NFIB R388 and the subsequent recruitment of the methylation reader TRIM29." (PMID 36690626, 2023). "We examined the CARM1-NFIB regulatory module in SCLC by immunostaining human tumor samples for CARM1, NFIB and NFIBme2a." (PMID 36690626, 2023). "In OXA-resistant xenograft tumor models, Circ_0082182 mediates the miR-326/NFIB axis, promoting tumor growth." (PMID 36950552, 2023). "We further revealed that NFIB knockdown suppressed the in vivo tumor growth of both SW480 and HT29 cells." (PMID 37491379, 2023). "Several factors, including EZH2, SFTPC, IGFBP5, ELN and EDN2, are regulated by NFIB, which have considerate values in the tumour microenvironment, advancing cancer impulsiveness, angiogenesis, migration and spread." (PMID 37845675, 2023). "Both the loss of CARM1 and the mutation of the CARM1 methylation site on NFIB in the TKO mouse model resulted in dramatically reduced lung tumor burden, as well as the levels of the tumor cell proliferation biomarker, phospho-H3." (PMID 36690626, 2023). "Recently, NFIB was identified as an oncogenic molecule in several cancers, which is highly expressed in tumor cells and modulates cellular proliferation, migration, invasion, and apoptosis." (PMID 35409172, 2022). "The results showed that CAFs in P-LNs were associated with the high expression of NFIB, IGLC2, IGHG4, C7, and CCL19, while CAFs in tumor 3 had high expression of DIO2, LGALS1, WNT5A, NEAT1, and MMP11 in the tumor." (PMID 36569924, 2022). "Further transcriptomic sequencing revealed that NFIB knock out leads to upregulation of urea cycle enzymes both in tumor tissue and normal liver tissue." (PMID 35655758, 2022).